NR3C1 (nuclear receptor subfamily 3 group C member 1)
Diseases named in the same sentence as NR3C1 in open-access papers (continued):
Sharing a sentence is not in itself a finding about the gene and the disease.
pancreatic cancer (10 papers, 2017 to 2026). "It has been confirmed that NR3C1 in pancreatic cancer is highly regulated by upstream miR-1270, and silencing NR3C1 can inhibit the malignant phenotype of pancreatic cancer cells." (PMID 40959664, 2025). "NR3C1 expression was displayed to be highly increased in pancreatic tumor tissues and cell lines (SW1990 and PANC-1), in comparison to normal tissues and normal cell line (hTERT-HPNE)." (PMID 36797317, 2023). "Similarly, based on analysis of the International Cancer Genome Consortium (ICGC) data, higher expression of NR3C1 correlated with worse survival in pancreatic cancer patients." (PMID 34873175, 2021). "Similarly, analysis of the gene expression data from The Cancer Genome Atlas (TCGA) revealed a positive correlation of NR3C1 mRNA levels with CD274 (encoding PD-L1) mRNA levels and a moderate inverse correlation of NR3C1 mRNA levels with HLA-A mRNA levels in pancreatic cancer." (PMID 34873175, 2021).
adenoma (9 papers, 2008 to 2024). A neoplasm arising from the epithelium. "Adenomas causing CD have higher expression of hsa-miR-124-3p and hsa-miR-135-5p and lower expression of their target genes NR3C1 and NR3C2." (PMID 35270010, 2022). "Objective of the present study was to report on constitutive and CRH- and dexamethasone-regulated POMC, CRH (CRH-R1), and glucocorticoid receptor (NR3C1) gene expression in a large series of human corticotrope adenomas." (PMID 27220856, 2017). "It is more difficult to predict the functional impact on colorectal tumorigenesis of the striking downregulated expression of the glucocorticoid receptor gene NR3C1 in all the adenomas we examined." (PMID 24472434, 2014). "Mutations of NR3C1 have been described in glucocorticoid resistance syndrome in association with bilateral adrenal hyperplasia; Next Genome Sequencing studies have then found rare loss-of-function NR3C1 mutations in ACTH-secreting adenomas." (PMID 35743266, 2022). "As observed with NR3C1, TSC22D3 transcripts are reduced in adenoma versus normal tissue but further induced at the adenoma-to-carcinoma progression; they strongly correlate with PRNP levels, including in the large GSE39582 dataset and are enriched in CMS4 CRC." (PMID 38589873, 2024). "ADAMTS1, CDKN2A, CRABP1, MLH1, NR3C1, RUNX3, and SCGB3A1 showed increasing methylation frequencies from adenomas to carcinomas, while HOXA9, MAL, and MGMT displayed overall equal methylation frequencies in all tumor subgroups." (PMID 19117505, 2008).
autoimmune disease (9 papers, 2014 to 2025). A disorder resulting from loss of function or tissue destruction of an organ or multiple organs, arising from humoral or cellular immune responses of the individual to their own tissue constituents. "Although the association between rs6198 NR3C1 SNP and decreased steroid sensitivity is known, its role in autoimmune diseases remains undefined." (PMID 34831409, 2021). "The association between rs17209237 NR3C1 and steroid sensitivity in autoimmune disorders was described in two studies." (PMID 34831409, 2021). "Moreover, certain NR3C1 polymorphisms associated with altered GR sensitivity or resistance have been reported to potentially contribute to the risk of developing specific autoimmune diseases." (PMID 40452801, 2025). "Recent studies suggest that NR3C1 polymorphisms could be involved in the pathogenesis of autoimmune disorders and have an impact on the GC treatment’s outcomes." (PMID 34831409, 2021). "Some investigations have suggested a relationship between NR3C1 SNPs rs6189/rs6190, rs41423247, and rs6198 and autoimmune diseases, but studies on GD are still lacking." (PMID 37189773, 2023).
bladder cancer (9 papers, 2016 to 2024). "This is especially prevalent in bladder cancer, where our reanalysis of published data indeed indicated the repression of NR3C1 expression by FOXA1." (PMID 38015476, 2024). "Previous studies showed that circRNA NR3C1 and circRNA 100284 can regulate the cell cycle of bladder cancer cell by inhibiting or promoting cyclin D1 respectively, thereby affecting the progress of bladder cancer." (PMID 33656636, 2022). "The glucocorticoid receptor (NR3C1, GR), a nuclear hormone receptor, regulates the expression of genes associated with inflammation and plays a role in suppressing cell proliferation in bladder cancer." (PMID 38254939, 2023). "Our analysis revealed a network of TFs whose activity could be essential to Basal bladder cancer biology, including HMGA2, KLF7, NR3C1 and ZBED2." (PMID 36944729, 2023).
colorectal cancer (9 papers, 2007 to 2025). A primary or metastatic malignant neoplasm that affects the colon or rectum. "DNMT1-induced NR3C1 hypermethylation is associated with colorectal cancer cells, and NR3C1 restoration inhibits pro-angiogenic effects on the cells." (PMID 40995432, 2025). "Restoration of NR3C1 suppresses the angiogenic, proliferative, survival, and oncogenic activities of colorectal cancer cells." (PMID 40959664, 2025). "Recently, we showed that promoter hypermethylation of ADAMTS1, CRABP1, and NR3C1 was frequent among colorectal carcinomas and cell lines and to a certain extent in colorectal adenomas." (PMID 17623056, 2007).
lung carcinoma (9 papers, 2008 to 2024). "Its ten hub genes were extracted and confirmed in the literature; seven of them (UBC, SRC, SP1, MYC, STAT3, RB1, and MAPK1) were verified to be associated with lung cancer, while the remaining three genes, JUN, NR3C1, and GRB2, were potentially new candidate lung adenocarcinoma-related genes." (PMID 26402252, 2015).
melanoma (9 papers, 2012 to 2025). A malignant, usually aggressive tumor composed of atypical, neoplastic melanocytes. "Downregulation of NR3C1 (glucocorticoid receptor) is of interest, as melanoma cells have recently been shown to express this receptor and dexamethasone has an antiproliferative effect on these cells." (PMID 22745913, 2012). "The most consistent candidate drug treatments for invasive melanoma were glucocorticoid receptor (NR3C1) agonists, AXL inhibitors, PARP1 inhibitors and HDAC inhibitors, as target gene expression for drug families predicted to target invasive melanoma." (PMID 38183207, 2025). "Other genes such as NR3C1, AXL, PARP1 and several HDAC genes were consistently found in invasive melanoma." (PMID 38183207, 2025). "We then inoculated C57BL/6 mice with cells from NR1H3 or NR3C1 OE, NR2F6 KD, or control wild-type (WT) B16F10 melanoma lines; treated animals with anti–PD-1 antibodies; and evaluated them for responses to ICT." (PMID 37406115, 2023). "This analysis suggests several classes of drugs such as glucocorticoid receptor (NR3C1) agonists, AXL inhibitors, PARP1 inhibitors and HDAC inhibitors as the most consistently expressed candidate drug-treatments in invasive melanoma across all studies examined." (PMID 38183207, 2025). "Among NRs expressed in >10% of melanoma cells were NR1H3, NR3C1, NR2F6, and ESRRA." (PMID 37406115, 2023).
osteoporosis (8 papers, 2012 to 2025). A condition of reduced bone mass, with decreased cortical thickness and a decrease in the number and size of the trabeculae of cancellous bone (but normal chemical composition), resulting in increased fracture incidence. "The LASSO regression algorithm established an osteoporosis-related model, identifying six disease-related candidate core target genes (IGF1R, NR3C1, MAP3K1, BRAF, WNK4, CNR2)." (PMID 40692598, 2025). "Our study provides evidences that NR3C1 directly upregulates RANKL transcription in human cell lines and connects the missing link in the mechanism of RANK/RANKL/OPG imbalance of glucocorticoid induced osteoporosis." (PMID 33494362, 2021).
alcohol abuse (7 papers, 2012 to 2025). The use of alcoholic beverages to excess, either on individual occasions ("binge drinking") or as a regular practice. "The expression levels of nuclear receptor subfamily 3, group C, member 1 (glucocorticoid receptor, nr3c1), which was also identified to be regulated by miR-183, may be associated with alcohol abuse." (PMID 25017766, 2014). "Specifically, two studies investigating alcohol use found hypermethylation and lower expression of NR3C1 in post-mortem brain tissue of adult individuals with a history of alcohol use disorder." (PMID 34526487, 2021). "Indeed, a recent study of 26 SNPs across the NR3C1 gene in 4,534 adolescents identified several variants that were associated with onset of drinking and drunkenness by age 14, suggesting that genetic variation in NR3C1 can influence the risk of alcohol abuse in adolescence." (PMID 23584114, 2012). "In humans, methylation levels of Nr3c1 are affected in offspring of prenatal depressive mothers as well as subjects suffering from psychiatric disorders, including individuals with alcohol use disorder, victims of suicide, combat veterans of PTSD, and women with bulimia nervosa." (PMID 35296634, 2022). "The results also suggest that master regulators like the glucocorticoid receptor (Nr3c1) and Psip1 play a role in the motivation for alcohol in chronic dependence and are potential targets for novel medications in the treatment of chronic alcohol abuse." (PMID 25886852, 2015).
alcohol dependence (7 papers, 2014 to 2021). Physical and psychological dependence on alcohol. "Similarly, pharmacological compounds targeting NR3C1, including NR3C1 antagonists and modulators, have been found to possess therapeutic properties in intervention studies for alcohol dependence." (PMID 34526487, 2021). "Nr3c1/GR is a gene of key significance to the paradigm of alcohol dependence-induced excessive drinking; however, the results highlighted a previously unrecognized key role of dysregulation of the Nr3c1/GR regulon in the NAc and VTA in excessive drinking during protracted abstinence." (PMID 25886852, 2015). "The study focused on molecular networks of the glucocorticoid receptor, Nr3c1, and their role in alcohol dependence-induced drinking, and no cell type-specific analysis was performed." (PMID 34573170, 2021).
gastric cancer (7 papers, 2014 to 2025). A primary or metastatic malignant neoplasm involving the stomach. "First, though aberrant DNA methylation in the promoter regions of NR3C1 is well-defined epigenetic hallmark in gastric cancer." (PMID 29285253, 2017). "We found that rs12521436, rs33388 and rs4912913 in NR3C1 were significantly associated with gastric cancer risk." (PMID 29285253, 2017). "OVCAR3 proliferation relied on NR3C1 node that has already been described associated with liver metastasis of gastric cancer." (PMID 24597747, 2014). "To test this hypothesis, we conducted a case–control study including 1,113 gastric cancer cases and 1,848 controls to investigate the association of functional polymorphisms in NR3C1 with risk of gastric cancer in a Chinese population." (PMID 29285253, 2017). "Recently, it is noteworthy that expression of NR3C1 was found to be associated with liver metastasis of gastric cancer and it was high methylated in gastric cancer which might play a key role in the initiation and progression of gastric carcinoma development." (PMID 29285253, 2017). "For instance, in gastric cancer, researchers analyzed the SE landscape of 5-FU-resistant and 5-FU-sensitive cells and found that NR3C1 is the main TF driving SEs, with its high expression associated with 5-FU resistance." (PMID 41323740, 2025). "Clinical correlation and epigenetic regulation analyses revealed that the methylation of NR3C1 was highly correlated with mRNA expression in gastric cancer and that the correlation between NR3C1 and methylated erasure genes, the TET family, was high." (PMID 40995432, 2025). "Inhibiting NR3C1 or disrupting SEs restores the sensitivity of gastric cancer cells to 5-FU, underscoring the key contribution of LLPS in regulating SE-related chemoresistance." (PMID 41323740, 2025). "In this experiment, WGCNA and machine learning algorithms were used to predict CA2, HSP90AA1, and NR3C1, the core targets of white Atractylodes against gastric cancer." (PMID 40995432, 2025). "With protein expression tested in seven gastric cancer cell lines, NR3C1 was knocked down using three shRNA lentiviruses in HS‐746T cells and overexpressed with the NR3C1 vector in MKN45 and HS‐746T cells (HS‐746T‐OE and MKN45‐OE cells)." (PMID 39731339, 2025). "NR3C1 was identified as a potential methylation marker of Atractylodes macrocephala against gastric cancer." (PMID 40995432, 2025). "For instance, SE-driven Nuclear Receptor Subfamily 3 Group C Member 1 (NR3C1) forms phase-separated condensates that promote 5-fluorouracil (5-FU) resistance in gastric cancer." (PMID 41323740, 2025). "While NR3C1 is reported to be down-regulated in primary gastric cancer, its function in gastric cancer needs more exploration." (PMID 28603669, 2017). "In gastric cancer, there was a strong correlation between NR3C1 methylation and its mRNA expression, suggesting that methylation of NR3C1 may be involved in the regulation of its expression." (PMID 40995432, 2025). "Our study provided genetic evidence that NR3C1 might be involved in the development of gastric cancer and further highlight the importance of NR3C1 in tumorigenesis." (PMID 29285253, 2017). "Recently promoter of NR3C1 has been found to be high methylated in gastric cancer tissues which might be involved in the initiation of gastric carcinoma development." (PMID 29285253, 2017). "The NR3C1 promoter, on the other hand, was at high methylation levels in all four parts of the gastric tissue, and except for the gastric antrum (gastric sinus), the methylation levels were higher in the control group than in the gastric cancer group in the remaining three parts." (PMID 40995432, 2025). "NR3C1 can be used as a potential methylation marker of RAM for the prevention and treatment of gastric cancer." (PMID 40995432, 2025). "None of the promoter methylation expression levels of CA2, NR3C1, and HSP90AA1 were significantly different in gastric cancer." (PMID 40995432, 2025).
gastric cancer (continued). "However, NR3C1 and PARK2 were not included in the network, and therefore their function in gastric cancer requires further investigation." (PMID 28603669, 2017).
Stroke (7 papers, 2010 to 2025). Sudden impairment of blood flow to a part of the brain due to occlusion or rupture of an artery to the brain. "There was no statistical significance between stroke characteristics and telomere length, NR3C1, TNF-α, BDNF, MTNR1A, or MTNR1B expression." (PMID 38802847, 2024).
Adrenal insufficiency (6 papers, 2010 to 2023). Insufficient production of steroid hormones (primarily cortisol) by the adrenal glands. "Thus, similar to ovarian insufficiency, adrenal insufficiency also exerted more intensive effects or more detrimental impact on SAT than VAT by inactivating the Nr3c1 signaling." (PMID 36768630, 2023).
Arthritis (6 papers, 2013 to 2023). Inflammation of a joint. "Among 35 MD-associated genes with drug-interaction data, four MD-specific genes interacted with drugs associated with arthritis: NR3C1 (N = 6), NRG1 (N = 2), CD40 (N = 2), TYR (N = 1)." (PMID 34603368, 2021).
cognitive decline (6 papers, 2021 to 2025). "Increased NR3C1 activation has been shown to cause neuronal damage and cognitive decline, modulate Aβ metabolism, and influence neuroinflammation, further linking it to AD pathogenesis." (PMID 39796199, 2025). "Longitudinal studies of patients with psychosis are needed to provide insights into causal associations between epigenetic regulation of the NR3C1 gene, psychotic disorders, and cognitive decline." (PMID 33284958, 2021).
colon carcinoma (6 papers, 2017 to 2025). "Of note, NR3C1 was greatly downregulated in colon cancer, and miR-19b could suppress NR3C1 expression to strengthen oxaliplatin resistance and colon cancer malignant progression." (PMID 36797317, 2023). "However, NR3C1 targeted by miR-19b was reported to be downregulated in colon cancer, and NR3C1 overexpression relieved oxaliplatin chemoresistance by regulating PI3K/AKT/mTOR pathway." (PMID 36797317, 2023). "Therefore, although TF E2F7 display opposite regulation effect on GFRA1 when comparing with NR3C2 and NR3C1, it did not have a competitive role with them in colon cancer." (PMID 32849837, 2020).
endometriosis (6 papers, 2015 to 2025). The growth of functional endometrial tissue in anatomic sites outside the uterine body. "NR3C1, encoding the glucocorticoid receptor, is associated with enhanced oxidative stress responses in endometriosis." (PMID 41492385, 2025). "Upregulation of IL1RL1, IL6ST, TNFRSF1B, and NR3C1 has been described in women with endometriosis." (PMID 38069001, 2023). "Our study indicates that PFAS may regulate the expression of oxidative stress-related genes, such as NR3C1 and PGR, disrupting the normal function of endometrial cells and promoting the development of endometriosis." (PMID 41492385, 2025).